TNF (tumor necrosis factor)
Diseases named in the same sentence as TNF in open-access papers (continued):
Sharing a sentence is not in itself a finding about the gene and the disease.
rheumatoid arthritis (continued). "In turn, long-term anti-TNF treatment (e.g. in patients with rheumatoid arthritis) while increasing the overall risk of herpes zoster, seems to reduce the incidence of PHN." (PMID 25127283, 2014). "Various reports have indicated that cytokines such as TNF-α, IL-1β and IL-6 play key roles in driving the inflammation and synovial cell proliferation characterizing rheumatoid arthritis-associated joint destruction." (PMID 25229347, 2014). "Activated macrophages are also believed to play a critical role in the pathogenesis of other diseases including rheumatoid arthritis, where release of cytokines, particularly TNF-α, instigates immunological reactions that cause destruction of synovial tissue." (PMID 23468959, 2013). "The relevance of TNF-α in human disease is underlined by the efficiency of TNF-α neutralizing therapy for the treatment of rheumatoid arthritis." (PMID 23762085, 2013). "TNFα ablation, by contrast, prevents both inflammation and bone loss in TNFα transgenic mice, and pharmacological TNFα inhibitors, such as TNFα receptor decoy receptors, are effective agents for amelioration of rheumatoid arthritis in human patients." (PMID 24278766, 2013). "In particular, dysregulated TNF-α production and release are implicated in a wide range of inflammatory diseases such as rheumatoid arthritis and Crohn's disease." (PMID 24349023, 2013). "In fact, a NASH patient was reported who experienced a rapid normalization of liver injury during the treatment of associated rheumatoid arthritis with a humanized anti-TNF Ab." (PMID 23372642, 2013). "The objective of this study was to determine if anti-TNF therapy is associated with an increased occurrence of serious skin and soft tissue infections requiring hospitalization in patients with rheumatoid arthritis." (PMID 24498926, 2013). "For example, systemic lupus erythematosus (SLE) and rheumatoid arthritis (RA) are associated with abnormally increased pro-inflammatory cytokine production by B cells, including TNF-α." (PMID 23505586, 2013). "TNF-α overexpression has been implicated in acute and chronic inflammatory diseases, such as septic shock, bowel disease, Crohn's disease, rheumatoid arthritis, atopic dermatitis, psoriasis, and BD." (PMID 24453431, 2013). "The progression of rheumatoid arthritis is accelerated by proinflammatory cytokines and chemokines, and tumor necrosis factor-α (TNF-α) and interleukin-1β (IL-1β) are reported to be associated with the progression of rheumatoid arthritis." (PMID 23442977, 2013). "Tumour necrosis factor (TNF)-α, an important cytokine in innate immune responses, has been implicated in several chronic inflammatory diseases including rheumatoid arthritis and Crohn's disease with anti-TNFα therapy proving useful in these conditions." (PMID 23189057, 2012). "Despite adjustment on the condition, some heterogeneity remains and it is difficult to conclude on the cancer risk regarding a specific indication for which TNF-α antagonists are widely used, such as rheumatoid arthritis." (PMID 23155441, 2012). "The aim of this survey was to assess cancer risk on TNF-α antagonists in adult rheumatoid arthritis patients, including the five marketed drugs (infliximab, etanercept, adalimumab, golimumab and certolizumab) used in line with the New Drug Application." (PMID 23155441, 2012). "Most of the available information is about patients with rheumatoid arthritis, in whom the risk of tuberculosis is 4–10-fold increased with the use of TNF antagonists." (PMID 22666281, 2012). "This study is the largest RCT MA devoted to investigate a putative excess cancer risk in adult rheumatoid arthritis patients exposed to TNF-α antagonists." (PMID 23155441, 2012). "In rheumatoid arthritis, presence of a soluble PD-1 isoform in serum was linked with disease activity characterized by rheumatoid factor in serum and TNF in synovial fluid levels." (PMID 22532845, 2012).
rheumatoid arthritis (continued). "Disturbances in TNF-α metabolism have been well documented and found to be associated with several other autoimmune and infectious diseases such as rheumatoid arthritis, systemic lupus erythematosus, crohn’s disease, cerebral malaria and lesihmaniasis." (PMID 23284977, 2012). "A study of all anti-TNF α agents in patients with rheumatoid arthritis showed that there was a significant overall risk of increased serious infections of the elderly over age 65 compared to younger cohorts." (PMID 22685455, 2012). "So, we conducted a new MA of RCTs to assess the cancer risk of TNF-α antagonists in adult rheumatoid arthritis patients, including the five drugs marketed." (PMID 23155441, 2012). "Osteoblasts also express high levels of the TNFR-1 and engagement with its ligand TNFα has been implicated in a wide spectrum of bone diseases including osteoporosis and rheumatoid arthritis." (PMID 21525984, 2011). "Even more alarming, anti-TNFα therapy in rheumatoid arthritis patients has been associated with the onset of monophasic demyelination including optic neuritis that subsided after treatment withdrawal and with the onset of MS." (PMID 21812954, 2011). "As a group, rheumatoid arthritis (RA) patients exhibit increased risk of infection, and those treated with anti-tumor necrosis factor (TNF) therapy are at further risk." (PMID 22177419, 2011). "A cohort (n = 503) from the Brigham Rheumatoid Arthritis Sequential Study was examined to identify clinical predictors associated with discontinuation of TNF inhibitors." (PMID 21624184, 2011). "An 87-year-old woman with severe rheumatoid arthritis sought treatment for weight loss, cough, night sweats, and dyspnea 1 year after starting anti–TNF-α treatment." (PMID 21392437, 2011). "Another common context for pathological bone loss is rheumatoid arthritis, in which inflammatory mediators such as TNFα promote OC differentiation and activation leading to local osteolysis." (PMID 21151480, 2010). "The method was then applied to identification of single-nucleotide polymorphisms (SNPs) associated with responses to anti-tumor necrosis factor (TNF) agents in patients with rheumatoid arthritis (RA) and active disease." (PMID 20691091, 2010). "Patients with rheumatoid arthritis (RA) have an increased risk of infection and this risk appears to be higher with anti-TNF (tumor necrosis factor) agents." (PMID 20398273, 2010). "In contrast, there is a rather indisputably strong association between the content of TNF-α in synovial fluid and disease activity such as in rheumatoid arthritis." (PMID 21192818, 2010). "The most common underlying medical indication for anti–TNF-α therapy was rheumatoid arthritis (n = 73, 75%), followed by other inflammatory diseases." (PMID 19861045, 2009). "For example, an increased risk of malignancy has been reported with TNF-alpha blockers, which are used primarily in the treatment of rheumatoid arthritis (RA)." (PMID 20016776, 2009). "In 2008, the Food and Drugs Administration required manufacturers of TNFα antagonists to strengthen their warnings about the risk of serious fungal infections in patients with rheumatoid arthritis (RA)." (PMID 19886992, 2009). "Since then, TNF has been linked to a number of auto-immune and inflammatory disorders including; rheumatoid arthritis, inflammatory bowel disease, and psoriasis, to name a few." (PMID 19133137, 2009). "Rheumatoid arthritis confers a higher baseline risk infections, and when patients are treated with anti-TNF therapy, the increased risk of infection has been extensively studied and debated." (PMID 19046446, 2008). "TNF-α enhancement by IL-7 is also present in other pathological conditions, characterized by a local and/or systemic bone loss, such as rheumatoid arthritis or postmenopausal osteoporosis." (PMID 17205128, 2006).
rheumatoid arthritis (continued). "IL-1β and TNF-α are clearly implicated in the pathogenesis of rheumatoid arthritis (RA) since blockage of their activities by antibodies or receptor antagonists is beneficial for patient treatment." (PMID 16846531, 2006). "Abnormal vitamin B6 status in rheumatoid arthritis has been associated with spontaneous tumor necrosis factor (TNF)-α production and markers of inflammation, including C-reactive protein (CRP) and erythrocyte sedimentation rate." (PMID 16277693, 2005). "The TNF+488A has been previously associated with rheumatoid arthritis and common variable immunodeficiency in addition to prostate cancer." (PMID 12966432, 2003). "Excess amounts of TNFα expressed in cells have been mainly associated with the development of immune diseases, in particular in psoriasis, Crohn's disease and rheumatoid arthritis." (PMID 41551713, 2026). "Therapy targeting TNF-alpha is the hallmark in managing conditions such as rheumatoid arthritis." (PMID 41598522, 2026). "Previous studies have suggested that TNF-α expression may be associated with altered pSTAT3 levels in other chronic autoimmune conditions, such as rheumatoid arthritis." (PMID 41030441, 2025). "As for the therapeutic agents used in the treatment of rheumatoid arthritis, such as TNF inhibitors, they may contribute to an increased risk of developing non-small cell lung cancer." (PMID 40724620, 2025). "Consequently, numerous studies initially examined this association in rheumatoid arthritis (RA), where TNF inhibitors had been introduced earlier, but the findings were inconsistent." (PMID 41302997, 2025). "Allele G was associated with a worse response to TNF blockers in people with rheumatoid arthritis." (PMID 41346622, 2025). "In our study of 71 drug-associated CTCL patients, 15 were treated with TNF-α inhibitors for a range of underlying autoimmune conditions, including psoriasis, psoriatic arthritis, Crohn's disease, ankylosing spondylitis, rheumatoid arthritis, and ulcerative colitis." (PMID 40226161, 2025). "Chronic inflammatory states, such as those observed in rheumatoid arthritis, inflammatory bowel disease, and systemic lupus erythematosus, are strongly associated with elevated levels of pro-inflammatory cytokines, including IL-6 and TNF-alpha." (PMID 40003660, 2025). "Another meta-analysis conducted on individuals of European population assessed the association between SNPs and response to anti-TNF-α therapy across major autoimmune diseases, including psoriasis, rheumatoid arthritis, inflammatory bowel disease, and spondyloarthritis." (PMID 40469293, 2025). "Next, Kyoto Encyclopedia of Genes and Genomes (KEGG) pathway enrichment analysis revealed down-regulated genes associated with c-type lectin receptor signaling pathway, rheumatoid arthritis, TNF signaling pathway, Toll-like receptor signaling pathway, and cytokine–cytokine receptor interaction." (PMID 39902346, 2025). "The development of rheumatoid arthritis (RA) and osteoarthritis (OA) is closely linked to inflammatory mediators, including TNF-α, interleukins (ILs), synovial fibroblasts (fibroblast-like synoviocytes (FLS)), macrophages, and ROS produced by activated polymorphonuclear leukocytes." (PMID 40430897, 2025). "Increased glycated TTR and RAGE protein levels have been found in patients suffering from rheumatoid arthritis, in association with increased levels of the pro-inflammatory cytokines IL-1β, IL-6, and TNF-α, suggesting a role of TTR/RAGE in this inflammatory disorder." (PMID 39766257, 2024). "Reports of DIL associated with anti-TNFα inhibitors are most common in rheumatoid arthritis patients, but cases have also been reported in Crohn's disease, ulcerative colitis, psoriatic arthritis, and ankylosing spondylitis, indicating no disease-specific predisposition." (PMID 39618753, 2024). "Interestingly, a study compared the risk of developing NMSCs under anti-TNF-α agents in patients with psoriasis and rheumatoid arthritis (RA)." (PMID 38730981, 2024).
rheumatoid arthritis (continued). "Moreover, future research is needed to establish the correlation between anti-TNF therapy, Hcy levels, vitamin D deficiency, and bone metabolism in patients with rheumatoid arthritis." (PMID 38672734, 2024). "TNF, which encodes a multifunctional proinflammatory cytokine in the TNF superfamily, is linked to diseases such as autoimmune disorders, insulin resistance, psoriasis, and rheumatoid arthritis." (PMID 39822742, 2024). "In addition, cytokines and proteases produced by mast cells are involved in the pathogenic process of rheumatoid arthritis, especially TNF, IL-1β, IL-17, and trypsin-like enzymes." (PMID 39144634, 2024). "TNF-α is a pro-inflammatory cytokine secreted by activated macrophages, T-lymphocytes, and natural killer cells, implicated in a spectrum of autoimmune diseases from rheumatoid arthritis to inflammatory bowel disease to uveitis." (PMID 39337619, 2024). "Notably, KEGG pathway analysis indicated enrichment in pathways associated with rheumatoid arthritis, IL-17 signaling, TNF-α signaling, and NF-kappa B signaling." (PMID 39518922, 2024). "However, TNF-α is also implicated in the pathogenesis of autoimmune diseases such as rheumatoid arthritis, psoriatic arthritis, and irritable bowel disease for which TNF-α inhibitors can be utilized for treatment." (PMID 39866364, 2024). "TNF-α inhibitors, which suppress Th1 responses, have been associated with an increased risk of tuberculosis activation since their introduction in treating rheumatoid arthritis and ankylosing spondylitis." (PMID 38392619, 2024). "Conversely, cluster 12 exhibited enrichment in signaling pathways such as protein digestion and absorption, ECM receptor interaction, TNF, apoptosis, and rheumatoid arthritis, which are commonly associated with cell apoptosis, pro-inflammation, and structural disruption." (PMID 39720254, 2024). "The most common primary disease involved was rheumatoid arthritis (31.86%), followed by psoriasis (20.35%) and Crohn’s disease (19.47%); however, a variety of other autoimmune conditions were also the causes for TNF-α inhibitor administration." (PMID 39336450, 2024). "Numerous studies have demonstrated the effectiveness of TNF-α, a cytokine with diverse effects on inflammation, in alleviating inflammation-related symptoms and signs associated with diseases, such as rheumatoid arthritis (RA) and complex regional pain syndrome." (PMID 38386244, 2024). "TNF-α inhibitors that suppress Th1 responses have been recognized to increase the risk of tuberculosis activation since their introduction in the treatment of rheumatoid arthritis and ankylosing spondylitis." (PMID 38137722, 2023). "In this meta-analysis of individual participant data from 3790 patients, the addition of certolizumab, a tumor necrosis factor α inhibitor, to conventional rheumatoid arthritis treatment was associated with an increased probability of reaching low disease activity in general." (PMID 37389866, 2023). "IBD and increased risk of rheumatoid arthritis, psoriasis, and asthma may be associated with tumor necrosis factor inhibitors." (PMID 38288127, 2023). "Also, previous studies have shown that TNFα antagonists are associated with risk reduction in cardiovascular events among patients with rheumatoid arthritis, psoriasis and psoriatic arthritis." (PMID 37763734, 2023). "Tumor necrosis factor α inhibitor (TNFαI) therapy is associated with a significant inhibition of radiographic progression, resulting in improved physical function and quality of life among patients with rheumatoid arthritis (RA)." (PMID 37629227, 2023). "It is widely thought that Adalimumab may mitigate the high level of TNF-α in rheumatoid arthritis patients, resulting in hair repigmentation, but the underlying mechanism warrants further research." (PMID 37781032, 2023).
rheumatoid arthritis (continued). "Interestingly, other diseases featuring chronic sterile inflammation and pathophysiological involvement of TNF-α including rheumatoid arthritis or psoriasis are associated with increased AF incidences." (PMID 34459957, 2022). "Neutralization of other pro-inflammatory cytokines, such as of TNF-α and IL-17, revealed inconsistent effects on cardiovascular end-points or worsened cardiovascular risk factors as exemplified by the increased risk for hypertension during anti-TNF therapy of rheumatoid arthritis." (PMID 35252400, 2022). "It is derived from the KEGG pathway enrichment analysis that differential genes were largely involved in the signaling pathway of interleukin 17 (IL-17), followed by other pathways like herpesvirus infection associated with Kaposi sarcoma, rheumatoid arthritis, and tumor necrosis factor (TNF)." (PMID 35902862, 2022). "However, dysregulation of TNFα-stimulated NF-κB signaling is implicated in wide ranges of diseases, including the autoimmune diseases rheumatoid arthritis (RA) and inflammatory bowel disease (IBD)." (PMID 35045889, 2022). "The target of this therapy is the molecular docking process that initiates the inhibition of proinflammatory cytokines such as cyclooxygenase-2 (COX-2), tumor necrosis factor alpha (TNF-a) and interleukin-1b (IL-1b) that reduce cardiovascular risk in rheumatoid arthritis." (PMID 36364403, 2022). "Abnormally elevated production, and/or sustained higher values of TNF-α, have been associated with autoimmune diseases, such as rheumatoid arthritis, multiple sclerosis, inflammatory bowel diseases, and chronic inflammatory disease states, such as sepsis, CKD, obesity, and diabetes." (PMID 35328704, 2022). "Antibodies blocking the major pro-inflammatory cytokine TNFα can cause new-onset neurologic symptoms in rheumatoid arthritis patients, associated with demyelinating lesions of the CNS, and may elicit immunogenic responses." (PMID 35890077, 2022). "Reducing T-cell immunity or its interaction with other critical factors such as TNF α may cause loss of structure in the rheumatoid nodule." (PMID 36422501, 2022). "A British Rheumatology Biology Society Rheumatoid Arthritis Registry study showed that patients exposed to anti-TNF therapy may have a reduced risk of colorectal cancer (hazard ratio, 0.52, 95%CI, 0.30–0.89)." (PMID 36618924, 2022). "Inflammation-induced bone loss, such as that associated with rheumatoid arthritis or periodontis, involves cytokine-mediated osteoclast activation; tumor necrosis factor-α (TNFα) may be the primary mediator in this regard." (PMID 35563167, 2022). "TNF-α is present in high concentrations at the site of in-flammation and has been studied for a long time as a pathological cause of various dis-eases and conditions, including sepsis, cancer, rheumatoid arthritis, ulcerative colitis, and Crohn’s disease." (PMID 36358984, 2022). "In keeping with this, a concept has also been proposed recently whereby individual patient-tailored algorithms are introduced to cope with patterns of variability to treatment regimens associated with loss of response to anti-TNFα therapies in rheumatoid arthritis." (PMID 35216184, 2022). "As the most widely used biologics in clinical practice, anti-TNF drugs not only reduced the risk of colorectal cancer in patients with IBD but also reduced the risk of colorectal cancer in patients with rheumatoid arthritis (with an adjusted hazard ratio of 0.51)." (PMID 36618924, 2022). "TNF-α is considered a critical cytokine in COVID-19–associated cytokine storm of acute inflammation, inflammatory bowel disease of chronic inflammation, and rheumatoid arthritis in autoimmune disease." (PMID 34677428, 2021).